SF3B1 (splicing factor 3b subunit 1)
Diseases named in the same sentence as SF3B1 in open-access papers (continued):
Sharing a sentence is not in itself a finding about the gene and the disease.
cancer (continued). "SF3b is essential for pre-mRNA splicing, and mutations in its largest subunit (SF3B1/SF3b155) are linked to cancer." (PMID 29383138, 2017). "Numerous studies have indicated that aberrant splicing patterns or mutations in spliceosome components, including the splicing factor 3b subunit 1 (SF3B1), are associated with hallmark cancer phenotypes." (PMID 28198434, 2017). "Aberrant forms of SF3B1 are also commonly associated with cancer and are predicted to be gain-of-function." (PMID 28445500, 2017). "We validated SF3B1 as a CYCLOPS gene and found that human cancer cells harboring partial SF3B1 copy-loss lack a reservoir of SF3b complex that protects cells with normal SF3B1 copy number from cell death upon partial SF3B1 suppression." (PMID 28177281, 2017). "Individual mutations are also found near other ubiquitination sites of SF3B1 (K182, K333, K785), suggesting that altered ubiquitination of the protein is important in cancer." (PMID 27175787, 2016). "We propose that loss of ubiquitination at K700 in SF3B1 leads to altered spliceosome assembly and causes aberrant splicing in cancer." (PMID 27175787, 2016). "Most cancer variation in SF3B1 in the TCGA dataset involves missense mutations, while stop codon and frame-shift mutations are not seen." (PMID 27175787, 2016). "Altogether, this study provides a better understanding of the mechanisms underlying splicing alterations induced by mutant SF3B1 in cancer, and reveals a role for alternative branchpoints in disease." (PMID 26842708, 2016). "Cancer-associated mutations in SF3B1 are missense mutations with three major hotspots targeting the fifth, sixth and seventh HEAT repeats at codon positions R625, K666 and K700, respectively." (PMID 26842708, 2016). "SF3B1 is the second most significant gene with PTM-specific cancer mutations (FDR p = 3.2 × 10–6 from ActiveDriver)." (PMID 27175787, 2016). "Mutations in the splicing factor SF3B1 are found in several cancer types and have been associated with various splicing defects." (PMID 25768983, 2015). "For cancers with SF3B1 mutations, we suspect that the size of the sterically protected region is slightly altered allowing for existing AG dinucleotides to be used as cryptic 3’SSs in hundreds of genes." (PMID 25768983, 2015). "While prior studies have reported a limited number of aberrant splicing events in SF3B1-mutated cancers, we have established that SF3B1 mutations are associated with usage of hundreds of atypical splice sites at the 3’ end of the intron." (PMID 25768983, 2015). "The majority of the 619 proximal cryptic 3’SSs were used in SF3B1-mutated samples in all three cancer types suggesting that the mechanism of cryptic 3’SS selection in SF3B1-mutated tumors is the same between different cancers." (PMID 25768983, 2015). "Here we have shown that a consequence of SF3B1 mutations in different cancer types is genome-wide selection of hundreds of cryptic 3’SSs." (PMID 25768983, 2015). "Targeting PUF60 may complement therapies for cancers harboring splicing factor mutations (e.g., SF3B1, U2AF1)." (PMID 41596295, 2026). "To date, studies of cancer-associated SF3B1 mutations have been carried out in blood cancer patient cells (MDS, AML, CLL), blood cells from mouse models, blood cancer cell lines (e.g., NALM and K562), or non-blood transformed cell lines (e.g., HeLa and HEK293 cells)." (PMID 41406100, 2025). "Nonetheless, we speculate that the similar mis-splicing patterns of SF3B1K700E mutation in hESCs and cancers cells reflect global roles of SF3B1 in the assembly and function of the pre-spliceosome." (PMID 41406100, 2025). "The SF3B1:p.Lys700Glu variant was predicted as a driver by the Cancer Genome Interpreter." (PMID 41294844, 2025). "While mutational landscapes in tumor or MDS samples may complicate the interpretation of the impact of SF3B1 mutation on tumorigenesis, our hESC model could be useful to uncover the mechanisms underlying gene dysregulation in splicing factor-mutant cancers." (PMID 41406100, 2025).
cancer (continued). "Among the different gene programs that could be exploited by cancer cells, mutation of splicing factors such as SF3B1 could increase the transcriptional output not only by affecting spicing itself but also by tuning RNA Pol II dynamics." (PMID 41406100, 2025). "SF3B1 is the most recurrently mutated RNA splicing gene in cancer." (PMID 39194178, 2024). "While splicing changes are highly context dependent and vary across cell lines and cancer types, work intersecting human and mouse model systems containing SF3B1 mutations have found two SF3B1 mis-spliced target mRNAs that are highly conserved: MAP3K7 and PPP2R5A." (PMID 39316554, 2024). "Notably, SF3B1 is one of the most mutated splicing factors across multiple types of cancer, often leading to extensive splicing aberrations." (PMID 39118304, 2024). "SF3B1 mutations frequently occur in cancer yet lack targeted therapies." (PMID 38997434, 2024). "Additionally, other residues of SF3B1 (e.g., R625, E902 and G742) were also found to be mutated and cancer-specific." (PMID 36983760, 2023). "However, in most diseases except MDS, but especially cancer, mutations in SF3B1 have been associated with poor prognosis and survival." (PMID 37875914, 2023). "Remarkably, all five of these SUGP1 mutations are located in the two SF3B1-interacting regions, and we thus wanted to investigate whether these cancer-associated mutations disrupt the interaction of SUGP1 with SF3B1." (PMID 37977822, 2023). "SF3B components, including SF3B1, have been implicated in cancer and various genetic disorders." (PMID 37875914, 2023). "In addition to being the most frequently mutated gene in MDS and MDS-RS, SF3B1 is amongst the most altered splicing factor across all cancers." (PMID 36857430, 2023). "The spliceosomal gene SF3B1 is frequently mutated in cancer." (PMID 37977822, 2023). "Despite the important role of mutant SF3B1 in tumorigenesis, the molecular basis by which the numerous SF3B1 cancer mutations lead to RNA missplicing remains unclear." (PMID 37977822, 2023). "The lack of overlap between the results of these studies suggests that the axes by which these circRNAs regulate cell behaviour are highly specific for individual cancer types; thus, their function may also be unique in SF3B1‐mutated MDS." (PMID 37408496, 2023). "Given that altered R-loop biogenesis is one of the underlying mechanisms for cancer development, we hypothesized that Sf3b1 mutation and Atm deletion synergistically lead to CLL development through R-loop accumulation." (PMID 37463047, 2023). "Likewise, SF3B1 supports HR-mediated DSB repair, with the most common SF3B1 cancer-associated mutation K700E promoting genome instability and DNA damage." (PMID 36980782, 2023). "Therefore, it seems likely that such additional mutational events are required in combination with SF3B1 mutations to produce an aggressive cancer phenotype." (PMID 37562845, 2023). "Moreover, mutations in BP trans-acting factor genes such as SF3B1 or U2 snRNA3 drive cancer development." (PMID 37949953, 2023). "Mutations in SF3B1, the gene coding the most commonly mutated spliceosome component across cancers, alters the splicing and promotes the decay of mRNA, coding a specific subunit of the PP2A serine/threonine phosphatase and increasing phosphorylation and, consequently, the stability of CMYC." (PMID 37296881, 2023). "The SF3B1-K700E mutation has been implicated in cancer progression." (PMID 37342192, 2023). "It is the first step that mainly determines the selection of correct branch sites, consistent with the fact that all SUGP1 cancer-associated mutations (as well as additional mutations described in this study) partially recapitulate the mutant SF3B1 missplicing pattern." (PMID 37977822, 2023). "Of all the known spliceosome components, SF3B1 is the most commonly mutated in human cancers." (PMID 35027467, 2022). "SF3B1 missense mutations are recurrent in several cancers, including UM." (PMID 35565242, 2022).
cancer (continued). "Moreover, the mutated SF3B1 functions as an anti-apoptotic factor which is regularly detected in various cancers in order to sustain the cell proliferation." (PMID 35327956, 2022). "Thus, although selective deletion of mutant SF3B1 has been reported to reverse aberrant splicing, it failed to translate to growth‐inhibitory effects on SF3B1‐mutated cancer cell lines." (PMID 34706158, 2022). "Given that SF3B1 is the most highly mutated member of this complex in a variety of cancers, we hypothesized that loss or mutation of this subunit would result in a DNA repair defect akin to what is observed in BRCA1-mutant tumors." (PMID 35027467, 2022). "Supporting this hypothesis, there are a series of SF3b1 mutations in the “exit channel” found in human cancers which cause a shift towards the use of degenerate upstream 3’ splice sites." (PMID 35143478, 2022). "Mutations in SF3B1 have been identified across several cancer types." (PMID 35027467, 2022). "SF3B1 represents the most frequently mutated component of the spliceosome in cancer." (PMID 35406598, 2022). "However, duon mutations have been identified in TPD53 and SF3B1 that also has correlation with cancer development and progression." (PMID 36215278, 2022). "Previously, many studies observed that SF3B1 is commonly mutated in human cancers, especially MDS." (PMID 33932092, 2021). "SF3B1, a core subunit of U2 component, is critical for branchpoint recognition and for the early stages of spliceosome assembly, and the most frequently mutated splicing gene in cancers." (PMID 33057152, 2021). "The most frequently mutated mRNA splicing factor genes in cancer are SF3B1 and SRSF2." (PMID 34065983, 2021). "The splicing factor 3B subunit-1 (SF3B1), which is involved in the branch site recognition during the pre-mRNA splicing process, is the most frequently mutated RNA splicing factor gene in cancer, and mutations in the HEAT domain of the SF3B1 gene have been detected in 4% of PDAC patients." (PMID 35582381, 2021). "In addition, nearly 80 splicing events have been reported to be specifically observed in cancers with SF3B1 mutations, many of which involve the recognition of ectopic 3′ ss." (PMID 33923658, 2021). "Alsafadi S and colleagues have indicated that SF3B1 is involved in the recognition of corresponding sequences when selecting splice sites in the splicing of RNA and its mutant is the most common mutational component of the spliceosome in cancer." (PMID 34445990, 2021). "Our results suggest that SF3B1 inhibitors and other tools affecting alternative splicing might be tested to eliminate cancer cells with mutations in SFs and also to control APOBEC mutagenesis in clinically relevant conditions." (PMID 33753867, 2021). "Aside from serine/arginine-rich protein-specific kinases, by far the most abundantly studied splicing factor as a target for cancer therapy is splicing factor 3B subunit 1 (SF3B1), which is frequently mutated in cancer, especially in hematological malignancies." (PMID 32545483, 2020). "Cancer-associated SF3B1 mutations are located within HEAT (Huntingtin, Elongation factor 3, protein phosphatase 2A, Targets of rapamycin 1) domains, which are involved in protein–protein interactions and clustered in hotspots, namely K700, E622, R625, H662, and K666." (PMID 33261131, 2020). "The cancer-associated mutations in SF3B1 also induce widespread changes to alternative splicing." (PMID 33348896, 2020). "Finally, we explore the options available for future research on the biological function and clinical significance of SF3B1 mutations in cancer." (PMID 32905346, 2020). "Thus, the functional consequences and mechanisms of SF3B1 mutations in cancers need to be further investigated." (PMID 32905346, 2020). "As hundreds of genes are associated with increased levels of cryptically spliced transcripts in SF3B1 mutants, it is to be expected that SF3B1 mutations may have widespread effects on cancer cells." (PMID 33585229, 2020).
cancer (continued). "SF3B1 mutations result in neomorphic activity, causing hundreds of alterations both through aberrant splicing and dysregulated gene expression in common alternative splicing signatures in different types of cancers." (PMID 32905346, 2020). "SF3B1 is a core component of the U2 spliceosome that is frequently mutated in cancer." (PMID 33348896, 2020). "In addition, the potential of SF3B1 or its mutations to serve as biomarkers or therapeutic targets in cancer is discussed." (PMID 32905346, 2020). "Cretu and co-workers speculated that some cancer-associated mutations in SF3b1 may result in structural perturbations of the HEAT repeat superhelix." (PMID 32320410, 2020). "SF3B1 is recurrently mutated in these cancers, and in fact, SF3B1 may be the most frequently mutated RNA splicing factor across all cancer types." (PMID 33143733, 2020). "Similarly, testing of two other human cancer-derived cell lines that carry SF3B1 K700E mutations (H-2595 and Panc0504) identified three or more copies of SF3B1." (PMID 30804405, 2019). "Thus, humanized sftb-1 nematodes obtained by this method would be very efficient as in vivo models to further understand the impact of SF3B1 mutations in cancer and as a platform for large-scale genetic and pharmacological screens." (PMID 31634348, 2019). "SF3B1 cancer-related mutations have been intensively studied in the past few years." (PMID 31634348, 2019). "Mutations in SF3B1 likely confer clonal advantages to cancer cells but they may also confer vulnerabilities that can be therapeutically targeted." (PMID 31634348, 2019). "SF3B1 is the most frequently mutated splicing factor in cancer." (PMID 31634348, 2019). "Cancer-associated mutations of the core splicing factor 3 B1 (SF3B1) result in selection of novel 3′ splice sites (3′SS), but precise molecular mechanisms of oncogenesis remain unclear." (PMID 30462273, 2019). "SF3B1 mutations have different prognostic associations in different types of cancers." (PMID 30847022, 2019). "The convergence on SF3B1 is intriguing, in that: MDM2 splicing appears to be particularly sensitive to SF3B1 suppression, SF3B1 is the target for multiple families of naturally occurring splicing modulators and there is an elevated SF3B1 mutation rate in cancer." (PMID 29796170, 2018). "Cryptic splice sites harboring such G- and the other purine-triplets tend to be enriched (2–9 folds over the disrupted canonical 3′ SS) and aberrantly used in cancer patients carrying mutations of the SF3B1 or U2AF35, factors critical for branch point (BP) or 3′ AG recognition, respectively." (PMID 30693020, 2018). "Therefore, the SF3B1 mutation-induced splicing factor changes are expected to further enhance aberrant splicing in cancer patients." (PMID 30693020, 2018). "One of these, the pre-mRNA splicing factor SF3B1, is also frequently mutated in cancer." (PMID 28177281, 2017). "Importantly, SF3B1 is mutated in several types of cancer, including chronic lymphocytic leukemia, uveal melanoma, breast, ovarian, and pancreatic cancers." (PMID 28445500, 2017). "Furthermore, cancers can harbor recurrent mutations in splicing factors, including gain-of-function mutations in SF3B1 that can sensitize cells to spliceosome modulatory drugs." (PMID 28177281, 2017). "Intriguingly, mutations in SF3B1 have also been associated with several distinct types of cancer." (PMID 28445500, 2017). "Interestingly, cancer-associated SF3B1 mutations have been recently linked to selection of aberrant upstream BP/PPT units that have shorter PPTs." (PMID 27566151, 2017). "In addition, AKT1 hotspot E17K mutations were found to be significantly more frequent in SF3B1 K700E mutated tumours (4/16) than in matched wild-type cancers (0/32, p = 0.009353, Fisher's exact test)." (PMID 25424858, 2015). "Differences in cryptic 3’SS usage due to varying gene expression may contribute to the divergent prognostic implications of SF3B1 mutation in various cancers." (PMID 25768983, 2015).
cancer (continued). "Here, we have examined mutations in the splicing factor SF3B1, a key component of the spliceosome, and identified a global splicing defect present in different cancers with SF3B1 mutations by comparing the expression of splice junctions using generalized linear models." (PMID 25768983, 2015). "This suggests that they could have a notable impact on the treatment of MDS, but also extends to a broader spectrum of clinical implications in other cancer types associated with the SF3B1 K700E mutation, underscoring the significance and widespread applicability of our findings." (PMID 38975181, 2024). "Hotspot mutations in SF3B1 induce use of cryptic 3′ splice sites typically located ∼10–30 nt upstream of the associated canonical 3′ splice sites by promoting recognition of alternative branch sites, and some of the resulting splicing errors contribute to severe cancer phenotypes." (PMID 37977822, 2023). "Cancer-associated SF3B1 mutations result in aberrant transcripts whose fate remains unknown." (PMID 35565242, 2022). "It is appealing to suppose that H3B achieves selectivity by having a greater affinity for mutant SF3B1, but it is unclear how this could occur considering that the site of the K700E mutation (and other common cancer-associated SF3B1 mutations) is located far from the SM binding site." (PMID 34681880, 2021). "These novel findings in Drosophila suggest that mutations at the same residue of SF3B1 in cancers would be mechanistically different in changes of alternative splicing on different substrate genes, and thus would be predicted to have different progression during the development of cancers." (PMID 34723968, 2021). "Indeed, SF3B1 is the most frequently mutated splicing factor in many cancers." (PMID 35008179, 2021). "In addition, studies in S. cerevisiae indicate that the corresponding cancer-related mutations in yeast SF3b1 also alter interactions between SF3b1 and other proteins, including Prp5 and SUGP1, suggesting that mutations in this region have pleiotropic effects in splicing." (PMID 32140746, 2020). "Importantly, SF3B1 mutations have been detected in many cancers." (PMID 31906144, 2019). "Thus, we decided to reproduce two other SF3B1 cancer-related mutations." (PMID 31634348, 2019). "Interestingly, the snRNPs which are the core components of the spliceosome seem to be rarely affected in cancer, while several mutations could be found in some cancer patients only at the SF3B1, U2AF1 or SNRNP70 genes." (PMID 29439487, 2018). "Thus, it is plausible that the dysregulation of SF3B1 and spliceosome activity by JA might lead to an imbalance in the splicing program in susceptible cancer cells, which may induce apoptosis by the accumulation of mis-spliced mRNAs into deleterious proteins." (PMID 28198434, 2017). "However, although preclinical studies with currently available SF3b‐targeting compounds have shown that these are more toxic to cancer cells than to healthy cells, we found that silencing the expression of SF3B1 and SF3B6 proteins also caused considerable toxicity in nonmalignant IMR‐90 fibroblasts." (PMID 28296343, 2017). "In addition to SF3B1 mutations, other genomic alterations in SF3B1, including copy number alterations, may also unveil novel cancer vulnerabilities." (PMID 28177281, 2017). "However, it is unknown whether SF3B1 mutation is associated with the same 3’SS selection defects in different cancers." (PMID 25768983, 2015). "In UVM, SF3B1 mutation drives aberrant RNA splicing of BRD9, a key component essential for the noncanonical BRG1/BRM-associated factor chromatin-remodeling complex, which is required to maintain SF3B1-mutant cancers." (PMID 40694421, 2025). "Cancer prognosis can be determined based on the mutation status of additional genes like BRCA1-associated protein-1 (BAP1), Splicing Factor 3B Subunit 1 (SF3B1), and eukaryotic translation initiation factor 1A x-linked (EIF1AX)." (PMID 40283643, 2025).